OPN3 (opsin 3)
Diseases named in the same sentence as OPN3 in open-access papers (continued):
Sharing a sentence is not in itself a finding about the gene and the disease.
sarcopenia (1 paper, 2026). Progressive decline in muscle mass due to aging which results in decreased functional capacity of muscles. "Thus, DECR1, HSD17B7 (AUC > 0.85), and OPN3 (AUC > 0.85) may serve as strong diagnostic biomarkers for sarcopenia." (PMID 41460756, 2026). "The FABP3 (P < 0.001), PECR (P < 0.01), and OPN3 (P < 0.001) mRNA expression markedly increased in sarcopenia versus control groups." (PMID 41460756, 2026). "The qPCR results demonstrated that FABP3 (P < 0.001), PECR (P < 0.01), and OPN3 (P < 0.001) expression markedly increased in D‐gal‐induced sarcopenia compared with control groups, whereas PCTP (P < 0.001), SREBF2 (P < 0.001), and PPARGC1A (P < 0.05) levels dramatically decreased." (PMID 41460756, 2026).
skin aging (1 paper, 2023). The gradual irreversible changes in structure of skin that occur as a result of the passage of time.. "Similar to the mechanism of UV-induced skin aging, this study started with the hypothesis that blue light may induce MMP expression in fibroblasts via OPN3-calcium-dependent signal transduction pathways." (PMID 36903418, 2023).
small cell lung carcinoma (1 paper, 2021). Small cell lung cancer (SCLC) is a highly aggressive malignant neoplasm, accounting for 10-15% of lung cancer cases, characterized byrapid growth, and early metastasis. "Knockdown of CCT5, PIP4K2A, EXO1, CMBL, OPN3, and KMO, genes within 200 kb up/downstream of the three SNPs that were corresponded with small cell lung cancer (SCLC) overall survival." (PMID 33869000, 2021).
thyroid carcinoma (1 paper, 2022). "The “arm-level gain” and “high amplification” of OPN3 in BRCA-luminal A (lumA), BRCA-luminal B (lumB) and THCA (thyroid carcinoma) were significantly associated with the infiltration value of cancer-associated fibroblasts (p < 0.05) based on the EPIC algorithm." (PMID 35180853, 2022).
tumor (12 papers, 2014 to 2025). "High expression of OPN3 in tumor tissue associated with poor prognosis and cancer-associated fibroblast infiltration." (PMID 36597133, 2023). "Next, using the TCGA project, the associations between OPN3 expression and the survival status of the 33 tumour types were estimated by log-rank tests." (PMID 35180853, 2022). "Consistently, a high immunohistochemical score of OPN3 was significantly associated with a poor prognosis among patients with 5 types of tumours." (PMID 35180853, 2022). "We also estimated the associations OPN3 expression between lymphovascular invasion, perineural invasion, and tumor infiltrative lymphocytes in ALMs." (PMID 33955704, 2021). "High OPN3 score was associated with presence of perineural invasion, increased tumor infiltrative lymphocytes (p = .0272 and p = .0144, respectively)." (PMID 33955704, 2021). "OPN3 has been implicated in tumor metastasis and drug sensitivity." (PMID 39131609, 2024). "Thus, OPN3 was closely related to enhancing cancer-associated fibroblasts that participate in modulating the function of various tumour-infiltrating immune cells." (PMID 35180853, 2022). "Altogether, OPN3 is associated with tumorigenesis and progression; however, the expression and role of OPN3 in other tumours remain unclear." (PMID 35180853, 2022). "With the exception of ASMTL, we observed upregulated mRNA levels of KIFC2, SMYD2, TFRC, and OPN3 in tumor tissues within these datasets." (PMID 39131609, 2024). "Its gene expression level and survival analysis were first evaluated among 33 tumour types by TCGA data, and further OPN3 aberrations were analysed across tumour types." (PMID 35180853, 2022). "In the TCGA cohort, a significantly reduced methylation level at the promoter region of OPN3 was observed in 3 types of tumours, including BLCA, LIHC, and LUAD, comparable to normal tissues." (PMID 35180853, 2022). "The expression and characterization of OPN3 were evaluated among 33 tumour types using The Cancer Genome Atlas (TCGA) dataset." (PMID 35180853, 2022). "Based on the analysis above, 347 samples from 5 types of tumours were collected and detected for the protein expression of OPN3 by immunohistochemical assay." (PMID 35180853, 2022). "Then, we validated the OPN3 expression signature in several tumours by our cohort and other CGGA and HCCDB databases." (PMID 35180853, 2022). "The results showed that tumours, in contrast to adjacent normal tissues, had higher RNA levels of OPN3 expression in nine out of the ten HCCDB datasets." (PMID 35180853, 2022). "Additionally, OPN3 DNA methylation levels in five types of tumours and normal tissues were assessed using UALCAN." (PMID 35180853, 2022). "Additionally, OPN3 expression was involved in cancer-associated fibroblast infiltration in 5 types of tumours, and promoter hypomethylation of OPN3 was observed in 3 tumour types." (PMID 35180853, 2022). "OPN3 was found to be related to tumor metastasis and drug sensitivity." (PMID 35739227, 2022). "Then, to assess whether OPN3 expression occurs in tumor cells, we determined that OPN3 was predominantly expressed in cancer cells by costaining of Melan‐A instead of stromal cells and lymphocytes." (PMID 33955704, 2021). "Therefore, the changes in OPN3 expression were associated with the EMT process, which may contribute to tumor metastasis in LUAD." (PMID 31802643, 2020). "We therefore combined methylation data from patient tumor tissues and cell lines following decitabine treatment to converge on six genes (CRIP1, G0S2, MLH1, OPN3, S100 and TUBB2A) as the classifier." (PMID 25391133, 2014). "The results showed that the protein level of OPN3 was higher in LIHC and STAD tumours than in adjacent normal tissues, consistent with its RNA expression level, whereas OPN3 scores of BLCA were not significantly different between tumour and adjacent normal tissues." (PMID 35180853, 2022).
cancer (9 papers, 2014 to 2023). A tumor composed of atypical neoplastic, often pleomorphic cells that invade other tissues. "In particular, we found that high expression of OPN3 in 7 types of cancer tissues was remarkably associated with poor prognosis." (PMID 35180853, 2022). "High expression of OPN3 was significantly associated with a poor clinical prognosis in five types of cancers." (PMID 35180853, 2022). "Together, these results suggested that the upregulation of OPN3 expression was associated with poor disease outcome in five types of cancers." (PMID 35180853, 2022). "In this study, the expression and characterization of OPN3 in different human cancers, as well as its association with clinical prognosis and potential functional roles was the focus." (PMID 35180853, 2022). "Additionally, the cancer-associated fibroblasts between different somatic copy number alterations (sCNAs) of OPN3 were assessed, including “deep deletion”, “arm-level deletion”, “diploid/normal”, “arm-level gain”, and “high amplification”." (PMID 35180853, 2022). "Furthermore, the expression of OPN3 was performed to verify the association between OPN3 expression level and clinical prognosis by immunohistochemical staining in cancer tissues, in which there was a significant difference between OS and different OPN3 expression levels from the TCGA dataset." (PMID 35180853, 2022). "Collectively, these data suggest that the expression of OPN3 at the RNA level was heterogeneous across human cancers." (PMID 35180853, 2022). "After adding the normal tissue in the GTEx (Genotype-Tissue Expression) dataset as controls, the expression difference of OPN3 was assessed between the normal tissues and cancer tissues." (PMID 35180853, 2022). "The OPN3 expression level was heterogeneous across cancers, yet a remarkable difference existed between OPN3 expression and patient overall survival among the 7 types of these 33 cancers." (PMID 35180853, 2022). "In conclusion, we demonstrated that the high expression of OPN3 was associated with a poor prognosis in BLCA, GBM, LGG, LIHC, LUAD, STAD and UVM cancers." (PMID 35180853, 2022). "Collectively, previous findings demonstrated that OPN3 plays multiple important roles in tumorigenesis, clinical prognosis, and treatment resistance in various cancers." (PMID 35180853, 2022). "The results indicated that the expression of OPN3 in LUAD cancer tissues was higher than that in normal lung tissues in both these experiments." (PMID 31802643, 2020). "In our study, we also demonstrated that the expression of OPN3 in LUAD cancer tissues was significantly higher than that in adjacent normal lung tissues." (PMID 31802643, 2020). "Next, we confirmed OPN3 overexpression in LUAD tissues by performing immunohistochemical staining in 114 pairs of cancer and adjacent tissues of LUAD patients." (PMID 31802643, 2020). "The reductive effect of cancer cell viability following blue LED irradiation was reversed by Opn3 knockdown or NF023 treatment." (PMID 29863164, 2018). "In addition, the effects of OPN3 on disease-free survival (DFS) were also tested in seven types of cancers." (PMID 35180853, 2022). "Furthermore, the biological role of OPN3 in cancers was evaluated via gene set enrichment analysis (GSEA)." (PMID 35180853, 2022). "Our study revealed the potential role of OPN3 in tumorigenesis and its prognostic value, suggesting that OPN3 might be a potential prognostic factor in these seven cancers." (PMID 35180853, 2022). "Therefore, we conducted GSEA to study the molecular mechanisms of OPN3 in carcinogenesis and progression, which demonstrated that OPN3 in 5 types of cancers remarkably correlates with modules of C7orf70 and C7orf25 and the “Ribosome” pathway." (PMID 35180853, 2022). "Additionally, the OPN3 RNA level and overall survival (OS) in relation to its expression level in 33 cancer types were estimated." (PMID 35180853, 2022).
cancer (continued). "However, the expression and function of OPN3, which is widely expressed in multiple tissues, remain unknown in human cancers." (PMID 35180853, 2022). "Thus, these promising findings indicated that OPN3 may be a potential indicator for the assessment of cancer prognosis." (PMID 35180853, 2022). "Furthermore, the enrichment analysis was mainly concentrated in C7orf70, C7orf25 and the “ribosome” pathway by GSEA in 5 types of cancers, indicating that OPN3 might affect tumorigenesis and progression by regulating gene expression and ribosome biogenesis." (PMID 35180853, 2022). "However, a comprehensive analysis of OPN3 across human cancers is unavailable." (PMID 35180853, 2022). "Therefore, upregulation of OPN3 may contribute to carcinogenesis in human cancers, especially in the seven cancer types." (PMID 35180853, 2022). "Thus, OPN3 may affect carcinogenesis and progression by regulating the ribosomal pathway in cancer." (PMID 35180853, 2022). "Emerging cell- or tissue-based evidence has demonstrated that opsin 3 (OPN3) mediates a variety of pathological processes affecting tumorigenesis, clinical prognosis, and treatment resistance in some cancers." (PMID 35180853, 2022). "The mean OPN3 score was the highest in cases with predominant pleomorphic cells while spindle cells group was the lowest, however, there was no statistical significance among different cell types in cancers (p = .461)." (PMID 33955704, 2021).
OPN3 also shares sentences with these, for which no sentence is quoted: cutaneous melanoma (3 papers); ovarian serous cystadenocarcinoma (2); pancreatic adenocarcinoma (2); rectal adenocarcinoma (2); uterine carcinosarcoma (2); uterine corpus endometrial carcinoma (2); acute myeloid leukaemia (1); basal cell carcinoma (1); cardiac arrest (1); colon adenocarcinoma (1); cutaneous squamous cell carcinoma (1); epilepsy (1); Insulin resistance (1); metabolic disorders (1); pulmonary disorders (1); testicular germ cell tumours (1); thymoma (1).